RBMS3 (RNA binding motif single stranded interacting protein 3)
Diseases named in the same sentence as RBMS3 in open-access papers (continued):
Sharing a sentence is not in itself a finding about the gene and the disease.
esophageal squamous cell carcinoma (10 papers, 2012 to 2024). Esophageal squamous cell carcinoma (ESCC) is a type of esophageal carcinoma (EC) that can affect any part of the esophagus, but is usually located in the upper or middle third. "Multiple investigations have established RBMS3 as a tumor suppressor gene in cancer, and its down‐regulation has been linked to unfavorable prognoses in malignancies such as esophageal squamous cell carcinoma, lung squamous cell carcinoma, nasopharyngeal carcinoma, and gastric cancer." (PMID 38618967, 2024). "It has been reported that RBMS3 plays a tumor suppressor role by downregulating c-Myc and β-catenin; low expression of RBMS3 predicts a poor prognosis in patients with GC and esophageal squamous cell carcinoma." (PMID 35361764, 2022). "Moreover, downregulation of RBMS3 in esophageal squamous cell carcinoma, lung squamous cell carcinoma, nasopharyngeal carcinoma and gastric carcinoma are frequently correlated with poor prognosis in patients and loss of RBMS3 contributed to chemoresistance in epithelial ovarian cancer." (PMID 30819235, 2019). "It has been reported that RBMS3 increased the expression of Prx1 transcription factor, which is a tumor suppressor in esophageal squamous cell carcinoma." (PMID 22957092, 2012). "Additionally, downregulated RBMS3 expression is associated with poor prognosis in lung squamous cell carcinoma, gastric cancer and esophageal squamous cell carcinoma, and downregulation of RBMS3 in ovarian cancer increased chemotherapeutic resistance." (PMID 34239534, 2021). "Besides, RBMS3 directly binds to the promoter region of c-Myc in esophageal squamous cell carcinoma (ESCC), and arrests cell cycle at the G1/S checkpoint." (PMID 27902480, 2017). "Interestingly, RBMS3, one of our candidate genes, has previously been shown to have a tumor-suppression function, through c-Myc downregulation, and contributed to poor prognosis in esophageal squamous cell carcinoma." (PMID 30871476, 2019).
nasopharyngeal carcinoma (10 papers, 2012 to 2024). A carcinoma arising from the nasopharyngeal epithelium. "Published papers indicate that RBMS3 can be viewed as a regulating factor of carcinogenesis in various cancers, including ovarian and nasopharyngeal cancers." (PMID 36769184, 2023). "In nasopharyngeal carcinoma, RBMS3 activates caspase-9 and PARP to promote tumor cell apoptosis in a mitochondria-dependent manner, repressing the microvessels formation via downregulating MMP2 and β-catenin." (PMID 37968257, 2023). "Studies conducted on nasopharyngeal cancer introduced RBMS3 as a potential regulator of the cell cycle." (PMID 36142783, 2022). "RBMS3 has a strong tumor suppressive role in nasopharyngeal carcinoma." (PMID 34804951, 2021). "From the clinical data, despite that down-regulated RBMS3 in lung squamous cell carcinoma (LSCC), nasopharyngeal carcinoma (NPC) and ESCC are found to strongly associate with unfavorable outcome, the expression and impacts of RBMS3 on GC progression is still unknown." (PMID 27902480, 2017).
gastric cancer (7 papers, 2019 to 2023). A primary or metastatic malignant neoplasm involving the stomach. "Studies have reported that higher RBMS3 expression in tumor cells is associated with more favorable disease outcomes in, inter alia, esophageal, nasopharyngeal, lung, and gastric cancer, which are tumor types that are often platinum-treated." (PMID 35743677, 2022). "All studies concerning the connection between the expression of RBMS3 and gastric cancer provided information about the downregulation of RBMS3 in this type of cancer." (PMID 36142783, 2022). "Research conducted on gastric cancer by Zhao seems to be coherent with Zhu’s results, showing an increased expression of E-cadherin and a decreased expression of N-cadherin and β-catenin in RBMS3-overexpressing gastric cancer cells." (PMID 36142783, 2022). "Moreover, in gastric cancer, RBMS3 overexpression significantly reduces the invasive ability of cancer cells." (PMID 37781074, 2023). "RBMS3 has been shown to reduce EMT and metastatic capacity of lung cancer cells and reduces EMT in gastric cancer cells through suppression of canonical Wnt signaling." (PMID 31694854, 2020).
lung carcinoma (5 papers, 2015 to 2023). "Clinically, we found that the expression of RBMS3 was strongly associated with the histological grade, clinical stage, and N stage of lung cancer." (PMID 37781074, 2023). "We found that RBMS3 is downregulated in lung cancer tissues and is strongly associated with clinical malignant pathological features and poor prognosis of patients." (PMID 37781074, 2023). "Moreover, we found that low expression of RBMS3 was positively associated with lung cancer's histological grade, clinical stage, and N stage." (PMID 37781074, 2023). "To further explore the effects of RBMS3 on lung cancer cell migration and invasion, we conducted wound healing, Transwell migration, and invasion assays." (PMID 37781074, 2023). "Our results indicate that RBMS3 is predominantly downregulated in most cancers, including lung cancer." (PMID 37781074, 2023). "To address this issue, we conducted IHC to measure the expression of RBMS3 in 75 lung cancer tissues and normal lung tissues." (PMID 37781074, 2023). "Subgroup analysis showed that high expression of RBMS3 significantly affected the overall survival of M0 (P=0.005), N1/N2 (P=0.018), and T3/T4 (P=0.006) lung cancer patients, respectively." (PMID 37781074, 2023). "Our findings demonstrate that RBMS3 acts as a tumor suppressor gene in lung cancer, suppressing the migration, invasion, and proliferation of tumor cells." (PMID 37781074, 2023). "In summary, the downregulation of RBMS3 expression holds significant prognostic implications for patients with lung cancer." (PMID 37781074, 2023). "Meanwhile, the results of multivariate Cox regression analysis showed that RBMS3 expression and T stage were independent prognostic factors in lung cancer patients (p<0.05)." (PMID 37781074, 2023). "Cox regression analysis revealed that RBMS3 was an independent prognostic factor for lung cancer patients." (PMID 37781074, 2023). "We then performed cell growth assays, including CCK8 and colony formation assays, to assess the impact of RBMS3 on lung cancer cell proliferation." (PMID 37781074, 2023). "In vitro experiments verified that RBMS3 inhibited lung cancer cell proliferation, invasion, and migration." (PMID 37781074, 2023). "Our findings revealed that the expression of RBMS3 can reliably predict the prognosis of lung cancer, with an AUC of 0.706." (PMID 37781074, 2023). "To investigate the biological function of RBMS3 in lung cancer, we conducted knockdown and overexpression experiments in NSCLC cell lines." (PMID 37781074, 2023). "This RBMS3-dependent mechanism sheds light on a promising therapeutic strategy for the treatment of lung cancer." (PMID 37781074, 2023). "Further research revealed that RBMS3 has an inhibitory effect on lung cancer cell proliferation and metastasis, suggesting its potential as a tumor suppressor gene." (PMID 37781074, 2023). "To elucidate the precise function and mechanism of RBMS3 in lung cancer, we conducted a series of in vitro experiments." (PMID 37781074, 2023). "Our findings indicate that RBMS3 functions as a tumor suppressor in lung cancer cells and acts as a mediator of AMPK signaling in these cells." (PMID 37781074, 2023). "The relationship between RBMS3 and clinical pathological features and prognosis of lung cancer was also analyzed." (PMID 37781074, 2023). "Our study has further uncovered a novel mechanism for the inhibition of lung cancer progression, whereby the activation of RBMS3 is mediated by AMPK activation." (PMID 37781074, 2023). "To validate these findings, we also analyzed data from the TCGA database, which consistently demonstrated lower expression of RBMS3 in lung cancer tissues." (PMID 37781074, 2023). "Another type of lung cancer discussed in the context of RBMS3 expression was non-small-cell lung cancer (NSCLC)." (PMID 36142783, 2022). "Depending on the type of lung cancer, different approaches to the role of RBMS3 were taken, highlighting different aspects of RBMS3’s effect on lung cancer progression." (PMID 36142783, 2022).
lung carcinoma (continued). "Upregulation of RBMS3 inhibits EMT in lung cancer through the inhibition of canonical Wnt signaling." (PMID 31694854, 2020). "We selected seven genes (CRP, GPC5, ACTA2, AGPHD1, SEC14L5, RBMS3, and GKN1) that previously reported link to lung cancer (LC) and genotyped single nucleotide polymorphisms (SNPs) of these genes in a case-control study." (PMID 25999661, 2015). "In this study, we aimed to investigate whether RBMS3 is essential for AMPK-mediated suppression of lung cancer migration and invasion." (PMID 37781074, 2023). "Additionally, we found that activation of the LKB1/AMPK axis promotes RBMS3 expression, thereby inhibiting lung cancer metastasis." (PMID 37781074, 2023). "Furthermore, our findings suggested that RBMS3 played an essential role in mediating AMPK's inhibitory effect on lung cancer invasion and migration." (PMID 37781074, 2023). "Our results showed that RBMS3 was significantly downregulated in lung cancer tissues." (PMID 37781074, 2023). "Taken together, our findings suggest that RBMS3 may serve as a promising tumor marker and prognostic indicator for lung cancer." (PMID 37781074, 2023). "Furthermore, prognosis analysis based on the TCGA database revealed that lung cancer patients with low expression of RBMS3 had poorer survival, and RBMS3 was an independent prognostic factor for lung cancer." (PMID 37781074, 2023). "Specifically, we found that in lung cancer cells, LKB1 positively regulates RBMS3 expression, and this effect is abolished upon AMPK knockout." (PMID 37781074, 2023). "In this study, we analyzed the expression of the RBMS3 in lung cancer patients and investigated the regulatory effect of LKB1/AMPK on RBMS3." (PMID 37781074, 2023). "However, the precise expression and function of RBMS3 in lung cancer remain unclear." (PMID 37781074, 2023). "IHC analysis was performed to assess the expression and localization of RBMS3 and LKB1 in lung cancer tissues and adjacent normal tissues." (PMID 37781074, 2023). "Statistical analysis showed significant decreases in the levels of RBMS3 (p<0.05) and LKB1 (p<0.05) in the lung cancer tissues compared to the adjacent normal tissues." (PMID 37781074, 2023). "However, the regulatory role of RBMS3 in the migration and invasion of lung cancer remains unclear." (PMID 37781074, 2023). "To elucidate the potential relationship between RBMS3 and LKB1, we collected samples from 65 lung cancer patients and 10 adjacent normal lung tissue patients." (PMID 37781074, 2023).
ovarian carcinoma (4 papers, 2021 to 2025). A malignant neoplasm originating from the surface ovarian epithelium. "Moreover, the loss of RBMS3 was associated with poor overall and relapse-free survival in epithelial ovarian cancer patients." (PMID 33685397, 2021). "Specifically, RBMS3 suppression was found to downregulate PD-L1 and enhance immune responses, while metformin treatment increased RBMS3 expression and promoted ferroptosis in ovarian cancer cells." (PMID 40417629, 2025).
amyotrophic lateral sclerosis (2 papers, 2018 to 2022). Amyotrophic lateral sclerosis (ALS) is a neurodegenerative disease characterized by progressive muscular paralysis reflecting degeneration of motor neurons in the primary motor cortex, corticospinal tracts, brainstem and spinal cord. "The versatility of RBMS3 reaches even the field of psychiatric health care and neurodegenerative diseases, since various authors have linked it to resistance to antidepressant therapy and susceptibility to schizophrenia and amyotrophic lateral sclerosis (ALS)." (PMID 36142783, 2022).
glaucoma (2 papers, 2020 to 2025). Increased pressure in the eyeball due to obstruction of the outflow of aqueous humor. "RBMS3 was not highlighted significantly in previous analyses, whereas CYP39A1 exhibited significant correlation with SE, indicating its potential direct relevance in glaucoma." (PMID 41042282, 2025).
non-small cell lung carcinoma (2 papers, 2021 to 2023). A group of at least three distinct histological types of lung cancer, including non-small cell squamous cell carcinoma, adenocarcinoma, and large cell carcinoma. "Additionally, we analyzed the RBMS3 expression levels in 1149 non-small cell lung cancer patients with various clinicopathological characteristics from TCGA." (PMID 37781074, 2023). "RNA-binding motif single-stranded interacting protein 3 (RBMS3), another member of the RBM proteins family, has been reported could suppress the morphogenesis of non-small cell lung cancer (NSCLC)." (PMID 34804951, 2021).
triple-negative breast carcinoma (2 papers, 2022 to 2025). An invasive breast carcinoma which is negative for expression of estrogen receptor (ER), progesterone receptor (PR), and human epidermal growth factor receptor 2 (HER2). "C James Block found that RBMS3 bound to and stabilized the mRNA of PRRX1, which in turn promoted the development of triple-negative breast cancers." (PMID 40155591, 2025). "Furthermore, RBMS3 has been reported to stabilise several members of the SMAD family such as SMAD2 in zebrafish and SMAD2, SMAD3 and SMAD4 in triple-negative breast cancer cells." (PMID 36421707, 2022).
acute kidney injury (1 paper, 2022). Sudden and sustained deterioration of the kidney function characterized by decreased glomerular filtration rate, increased serum creatinine or oliguria. "An association was identified between RBMS3 rs10663797 and acute kidney injury (coefficient −0.10 (95% confidence interval −0.13–−0.06), p-value 2.72 × 10−8)." (PMID 35743677, 2022).
autoimmune disease (1 paper, 2020). A disorder resulting from loss of function or tissue destruction of an organ or multiple organs, arising from humoral or cellular immune responses of the individual to their own tissue constituents. "Although RBMS3 has not been directly linked to SSc, SNPs in RBMS3 have been associated with risk of another autoimmune disease affecting connective tissue called Sjögren’s syndrome." (PMID 31694854, 2020).
bladder cancer (1 paper, 2022). "The results showed that the downregulation of RBMS3 in bladder cancer was specifically related to a better overall survival (OS), with a higher expression of RBMS3 implicating a poorer prognosis." (PMID 36142783, 2022). "The relationship between the expression of RBMS3 and bladder cancer is one of the most recently discussed in the literature." (PMID 36142783, 2022).
colon cancer (1 paper, 2024). "In order to elucidate the molecular mechanism underlying RBMS3's inhibitory effects on colon cancer progression, we performed RNA‐seq analyses on cells overexpressing RBMS3, cells with RBMS3 knocked down, and a control group." (PMID 38618967, 2024). "The precise role of RBMS3 in colon cancer remains elusive, and its underlying molecular mechanisms remain incompletely elucidated." (PMID 38618967, 2024). "Importantly, the downregulation of RBMS3 expression has been linked to enhanced growth and metastasis of colon cancer, implying that RBMS3 acts as an inhibitor in colon cancer development." (PMID 38618967, 2024). "The study conclusively ascertained that augmenting RBMS3 expression quells the proliferation, migration, and invasion of colon cancer cells." (PMID 38618967, 2024). "In our study, we have observed significant downregulation of RBMS3 in colon cancer tissues compared to normal tissues, as confirmed by IHC, Western blot, and qRT‐PCR." (PMID 38618967, 2024). "These discoveries indicate the potential pivotal role of RBMS1 and RBMS3 in the context of colon cancer." (PMID 38618967, 2024). "Our investigation primarily centered on elucidating the impact of RBMS3 on the proliferation of colon cancer cells." (PMID 38618967, 2024). "Utilizing MTT and EDU assays, we observed that overexpressing RBMS3 hindered the proliferation of colon cancer cells, whereas knockdown of RBMS3 promoted it." (PMID 38618967, 2024). "Our results consistently demonstrated that the overexpression of RBMS3 impeded the migration and invasion of colon cancer cells, while its knockdown facilitated these processes." (PMID 38618967, 2024). "Nevertheless, the precise molecular mechanisms by which RBMS3 operates in colon cancer remain enigmatic." (PMID 38618967, 2024). "Lastly, we assessed the impact of altered RBMS3 expression on LIMS1 mRNA stability in colon cancer cells treated with Actinomycin D, revealing that RBMS3 amplified the stability of LIMS1 mRNA." (PMID 38618967, 2024). "Despite an abundance of studies elucidating RBMS3's divergent roles in the genesis and advancement of various tumors, its involvement in colon cancer remains enigmatic." (PMID 38618967, 2024). "Overall, these findings strongly indicate that RBMS3 impedes the progression of colon cancer by governing the stability of LIMS1." (PMID 38618967, 2024). "Further investigation revealed a significant correlation between the expression of RBMS1 and RBMS3 and the clinical stage of colon cancer." (PMID 38618967, 2024). "In vitro and in vivo experiments have further demonstrated that upregulation of RBMS3 expression can restrict the cell proliferation, migration, and invasion of colon cancer cells." (PMID 38618967, 2024). "The investigation ascertained that RBMS3 inhibits the progression of colon cancer by regulating LIMS1." (PMID 38618967, 2024). "Our results unveiled a noteworthy reduction in the expression of RBMS1 and RBMS3 in colon cancer in comparison to normal colon tissues." (PMID 38618967, 2024). "The present investigation employed data analysis from TCGA and GTEx to unveil that RBMS3 expression demonstrated a diminished presence in colon cancer tissues when juxtaposed with normal colon tissues." (PMID 38618967, 2024). "In this study, we demonstrate that RBMS3 exerts an inhibitory influence on colon cancer progression by impeding the malignant phenotype of colon cancer cells." (PMID 38618967, 2024). "Serving as a potential inhibitor of colon cancer cell proliferation, migration, and invasion, RBMS3 modulates the mRNA stability of LIMS1, thereby exerting a suppressive influence on the advancement of colon cancer." (PMID 38618967, 2024). "Subsequently, we conducted MTT and Transwell migration experiments to investigate whether the downregulation of LIMS1 could counteract the inhibitory effects induced by RBMS3 overexpression on colon cancer cells." (PMID 38618967, 2024).